LGALS16 (galectin 16)
Description:
Binds lactose with high affinity. Strong inducer of T-cell apoptosis.
Tractability: No criterion of Open Targets' tractability assessment is met for any kind of drug.
Gene: Protein-coding gene on chromosome 19 (39,655,913 to 39,660,647, forward strand). Ensembl gene ENSG00000249861.
Gene Ontology:
Molecular function: lactose binding; carbohydrate binding
Biological process: positive regulation of T cell apoptotic process; positive regulation of programmed cell death
Genetic constraint (gnomAD): Loss-of-function variants: 14 observed, 11.23 expected, observed/expected ratio (o/e) 1.25, 90% interval 0.82 to 1.82. The upper end of that interval is the gene's LOEUF score, 1.82, which puts it in group 6 of 6, group 1 being the genes least tolerant of losing a copy. Missense variants: 194 observed, 162.42 expected, observed/expected ratio (o/e) 1.19, 90% interval 1.06 to 1.35. Synonymous variants: 64 observed, 53.52 expected, observed/expected ratio (o/e) 1.2, 90% interval 0.98 to 1.47.
Homologues: Orthologues: chimpanzee LGALS16 (99% identical), Caenorhabditis elegans lec-1 (26% identical), zebrafish lgals3b (25% identical), zebrafish lgals9l5 (25% identical), zebrafish lgals9l6 (25% identical), zebrafish si:dkey-95h12.2 (25% identical), zebrafish lgals9l4 (25% identical), Caenorhabditis elegans lec-12 (24% identical), Caenorhabditis elegans lec-3 (24% identical), Drosophila melanogaster galectin (24% identical), tropical clawed frog lgals9 (22% identical), zebrafish lgals9l3 (22% identical), and 23 more. Paralogues in human: LGALS13 (74% identical), LGALS14 (60% identical), CLC (52% identical), LGALS4 (28% identical), LGALS7 (28% identical), LGALS7B (28% identical), LGALS8 (26% identical), LGALS3 (25% identical), LGALS9 (20% identical), LGALS9B (20% identical), LGALS9C (20% identical), LGALSL (18% identical), and 4 more.
Diseases named in the same sentence as LGALS16 in open-access papers:
LGALS16 is named in the same sentence as 9 diseases in open-access papers, as found by Europe PMC text mining. Sharing a sentence is not in itself a finding about the gene and the disease. The quoted sentences say what the papers report.
Alzheimer disease (1 paper, 2021). A progressive, neurodegenerative disease characterized by loss of function and death of nerve cells in several areas of the brain leading to loss of cognitive function such as memory and language. "There are bioinformatics indications that the expression of LGALS16 changes in association with Alzheimer’s disease, chronic myeloid leukemia, breast cancer, B-cell lymphoma, and type 2 diabetes." (PMID 34944551, 2021).
diabetes (1 paper, 2021). "Our findings indicate that LGALS16 is detected by microarrays in diverse human cells/tissues and alters expression in association with cancer, diabetes, and brain diseases." (PMID 34944551, 2021).
preeclampsia (1 paper, 2021). Preeclampsia is a hypertensive disorder of pregnancy that is characterized by new-onset hypertension with proteinuria presenting after 20 weeks of gestation, and depending on mild or severe forms may initially present with severe headache, visual disturbances, and hyperreflexia. "Dysregulation of this placenta-specific gene cluster containing LGALS16 is associated with disorders such as preeclampsia, which can be highly fatal for both the mother and fetus." (PMID 34944551, 2021). "Although LGALS16 was not significantly impacted at the gene level in preeclampsia, there remain questions regarding regulation at the protein level, which cannot be properly addressed at this time due to the absence of commercially available specific galectin-16 antibodies." (PMID 34944551, 2021).
cancer (1 paper, 2021). A tumor composed of atypical neoplastic, often pleomorphic cells that invade other tissues. "Primary association of LGALS16 with placental tissue has been challenged by its detection in brain tissues and several cancer cell lines as followed from available microarray and RNA-seq databases." (PMID 34944551, 2021).
LGALS16 also shares sentences with these, for which no sentence is quoted: B-cell lymphoma (1 paper); brain diseases (1); breast carcinoma (1); chronic myeloid leukemia (1); type 2 diabetes (1).